ALB (albumin)
Diseases named in the same sentence as ALB in open-access papers (continued):
Sharing a sentence is not in itself a finding about the gene and the disease.
Hypoalbuminemia (continued). "These toxicokinetic changes were associated with increased hepatotoxicity in heterozygous albumin knockout mice for which serum albumin was reduced to a similar extent as in patients with severe hypoalbuminemia." (PMID 35962801, 2022). "Studies have shown that DPMAS combined with PE can supplement a certain amount of plasma to improve the coagulation function while actively supplementing albumin to reduce hypoproteinemia, effectively avoiding bleeding risks and hypoalbuminemia." (PMID 35368957, 2022). "Serum albumin is synthesized by the liver, and hypoalbuminemia usually occurs when the liver function is damaged or the body is malnourished, thus weakening the body’s immune defense ability." (PMID 36005195, 2022). "Laboratory investigations confirmed the diagnosis of ISCLS including the findings of hemoconcentration (peak hematocrit 73%), hypoalbuminemia (nadir serum albumin 1.8 g/dL), and a monoclonal IgG-kappa paraprotein (01–0.2 g/dL)." (PMID 36038904, 2022). "More active albumin administration during the perioperative period is recommended in burn patients with hypoalbuminaemia." (PMID 35097135, 2022). "In our study, hypoalbuminemia was detected only in 13 (5.9%) CRC patients, and both sarcopenia and myosteatosis associated with decreased albumin levels (p = 0.029 and p = 0.003)." (PMID 35566781, 2022). "Decreased albumin synthesis leads to hypoalbuminemia, which contributes to the development of edema by the transudation of fluids into extravascular spaces." (PMID 36072935, 2022). "Because hypervolemia results in dilutional hypoalbuminemia, we compared total fluid balance of each albumin group during CRRT." (PMID 35672868, 2022). "In view of this data, we suggest the co-administration of albumin and furosemide only in cases of diuretic resistance and moderate-severe hypoalbuminemia (2–2.5 mg/dL)." (PMID 35874534, 2022). "Proteinuria (≥0.5 g/g creatinine) was observed in all patients, and 75.9% of these patients had NS (massive proteinuria ≥ 3.5 g/d) and hypoalbuminemia (albumin ≤ 3.0 mg/dl)." (PMID 35685313, 2022). "Complicated with pulmonary tuberculosis, low preoperative albumin value and long operation time can lead to postoperative hypoalbuminemia in patients with thoracic and lumbar tuberculosis." (PMID 35571899, 2022). "Hypoalbuminemia, defined as serum albumin level <3.5 gr/dL, was present in 80% of patients (n = 136)." (PMID 35054049, 2022). "Although new data suggest that increased catabolism is a more frequent reason, hypoalbuminemia in chronic illness has traditionally been attributed to decreased albumin synthesis because of wasting and cachexia." (PMID 36589182, 2022). "The literature often addresses hypoalbuminemia in severe COVID-19, but the prognostic value of albumin is still underestimated." (PMID 35956107, 2022). "The electrophoresis showed a significant hypergammaglobulinemia, a slight hypoalbuminemia, and, consequently, a reduced albumin/globulin ratio." (PMID 36006315, 2022). "Hypoalbuminemia defined as serum albumin less than 35 g/L is commonly considered a representation of malnutrition." (PMID 35571899, 2022). "After STB surgery, patients have significantly reduced levels of postoperative albumin, and in one study, the incidence of postoperative hypoalbuminemia has been found to be 72.8%." (PMID 35187165, 2022). "One used 3 g/dl as the criteria for hypoalbuminemia while another used age-stratified criteria with albumin cut-off ranging from 3.4 to 3.7 g/dl." (PMID 36684211, 2022). "In the COVID-19 cases (C), probably due to low serum albumin levels (<3.5 g/dL, hypoalbuminemia), changes in protein conformation and dynamics imply the free rotation of 3-Maleimido-PROXYL, comparable to that of nitroxide in DMSO (protein-free sample)." (PMID 36552520, 2022). "At 1 year after BPD-DS, the level of albumin was below normal in one patient (albumin level ≥30 but <34.9 g/L), and one patient had severe hypoalbuminemia (albumin level <30 g/L)." (PMID 36684353, 2022).
Hypoalbuminemia (continued). "Homozygous mutant mice on both backgrounds exhibited hypoalbuminemia, but albumin levels were significantly lower in C3pde-Lama5E884G/E884G mice at this time point." (PMID 34774562, 2022). "Another possible explanation for the importance of ALB is that hypoalbuminemia reduces the inflammatory response that usually protects against infection, while the complete innate and adaptive immune responses depend on ALB." (PMID 35813227, 2022). "The mean preoperative serum albumin level (A1) of the cohort was 3.3 g/dl (range: 2.8 g/dl to 4.1 g/dl) with 57.14% (32/56) of the children (57.14%) having hypoalbuminemia on admission." (PMID 35706741, 2022). "The mean preoperative serum albumin level (A1) in this group was 3.25 gm/dl (range: 2.8 g/dl to 3.8 g/dl) with 55.55% (10/18) of the children (55.55%) having hypoalbuminemia on admission." (PMID 35706741, 2022). "Human albumin was selectively used in cases of previous hypoalbuminemia, extensive debulking, and mucinous ascites." (PMID 35399457, 2022). "Replacing CCI with serum albumin in the LR model, using three parameters only, provided similar results (OR of hypoalbuminemia 4.5; AUC 0.77)." (PMID 35268297, 2022). "Patients with cirrhosis and hypoalbuminemia often have ascites or edema when the plasma albumin concentration is lower than 30 g/L, and ascites is bound to occur when it is lower than 25 g/L." (PMID 35251204, 2022). "There were 1,078 (15.2%) patients in the pre-operative hypoalbuminemia group and 5,994 (84.8%) patients in the normal pre-operative albumin group." (PMID 36105581, 2022). "Similar finding was detected in the current work, where hypoalbuminemia represented 45.3% of the total inappropriate albumin indications in the retrospective phase." (PMID 35370698, 2022). "As hypoalbuminemia among adults is defined as serum albumin level below 3.5 g/dL, the majority of our study patients suffered from hypoalbuminemia." (PMID 35189828, 2022). "Even though hypoalbuminemia takes an important place in diagnosis, albumin level was normal in our patient." (PMID 36027830, 2022). "Laboratory results found to be potential predictors of HCC were thrombocytopenia (platelet count < 150,000/μL), hypoalbuminemia (albumin < 3.5 g/dL), ALT level < 80 U/L, total bilirubin ≥ 2.0 mg/dL, INR ≥ 1.7, and serum sodium level <140 mmol/L." (PMID 36431090, 2022). "There were 371 patients (98.7%) who had hypoalbuminemia, and the minimal serum albumin was 23.4 ± 5.1 g/L (range from 10 to 34 g/L, 325 cases/86.4% < 30 g/L)." (PMID 36552932, 2022). "In our ICU, it is standard of care to replace albumin in patients who received a high amount of crystalloid resuscitation fluid and in those with hypoalbuminemia." (PMID 35955987, 2022). "According to medical literature, COVID-19 patients with hypoalbuminemia are more likely to develop AKI than patients with normal serum albumin level as observed in this study as well." (PMID 35634634, 2022). "Similar results were mentioned in previous studies evaluating albumin use appropriateness in ICUs, where hypoalbuminemia represented from 23.4% to 36.2% of the inappropriate indications." (PMID 35370698, 2022). "Like many laboratory parameters, the historical definition of hypoalbuminemia is derived empirically from the distribution of serum albumin concentration in a representative population." (PMID 36362771, 2022). "LA which reduces transendothelial resistance, causing macromolecular capillary leakage, reacted with albumin and calcium, explaining the rapid hypoalbuminemia and hypocalcemia we note in humans and mice." (PMID 35502320, 2022). "Acutely, management with supplemental albumin, furosemide, potassium, and vitamin K was initiated to correct the presenting hypoalbuminemia, edema, and coagulopathy." (PMID 36683818, 2022). "Such hypoalbuminemia cannot be explained by reduced albumin synthesis, because albumin has a 25-day half-life." (PMID 35502320, 2022).
Hypoalbuminemia (continued). "A second study suggested that hypoalbuminemia (albumin <3 g/dL) and intensive care unit (ICU) admission were independent predictors of short-term mortality." (PMID 35711246, 2022). "Seventeen patients (26.2%) had mild hypoalbuminemia with serum albumin levels between 2.5 and 3.49 g/dl." (PMID 34734326, 2022). "The whole studied group (n = 9759) included patients with hypoalbuminemia (n = 2278), and a control group of patients with normal serum albumin (n = 7481)." (PMID 35268297, 2022). "It has been suggested that measured fructosamine should be corrected for albumin in the presence of hypoalbuminemia." (PMID 35213623, 2022). "In the stage of sepsis, albumin can indirectly contribute to immunity by providing nitrogen for globulin production, resulting in hypoalbuminemia and elevated globulin concentration." (PMID 36053443, 2022). "Hypoalbuminemia was common after the plasma volume had been restored, which at least temporarily contributes to the decrease in metabolic acidosis because albumin is a weak acid." (PMID 36038699, 2022). "For low-risk patients and high-risk patients, according to our research results, the preoperative albumin value should reach 40 and 44 g/L, respectively, to effectively avoid postoperative hypoalbuminemia." (PMID 35571899, 2022). "The present opinion aims to demonstrate the diagnostic utility and application of the SDSL-EPR method in the study of hypoalbuminemia and changes in albumin dynamics in cases of critically ill patients with COVID-19." (PMID 36552520, 2022). "Laboratory findings showed moderate anemia (hemoglobin, Hb 72 g/L), urinary protein 3+, and hypoalbuminemia (albumin, ALB 29 g/L)." (PMID 36034551, 2022). "The benefits and risks of supporting plasma oncotic pressure (i.e., synthetic colloids, canine plasma, human or canine albumin) should be carefully weighed in dogs with severe hypoalbuminemia and marked cavitary effusion." (PMID 36213409, 2022). "Based on these, and the mechanistic link of UFAs triggering synchronous hypocalcemia and hypoalbuminemia, we did a multivariate analysis to study the impact of calcium and albumin levels on mortality in a large retrospective hospitalized COVID-19 cohort." (PMID 35502320, 2022). "Applying the LR model to predict 1 yr mortality in HAD patients confirmed the power of age, CCI and albumin as predictors, with an OR for hypoalbuminemia of 3.40 (p < 0.01), and AUC for the model of 0.73." (PMID 35268297, 2022). "Heterozygous albumin knockout mice, where serum albumin is reduced to levels measured in patients with severe hypoalbuminemia, showed a markedly reduced OTA signal in blood compared to the wild-type mice." (PMID 35962801, 2022). "One possible reason is that the protein-binding rate of caspofungin is very high, and hypoalbuminaemia will reduce the binding of caspofungin to ALB, which will increase the CL of caspofungin in patients with hypoalbuminaemia." (PMID 36408257, 2022). "At present, modern medical treatment of hypoalbuminemia in liver cirrhosis is mainly to directly supplement exogenous albumin." (PMID 35251204, 2022). "Serum biochemical analysis revealed mild increase in total serum proteins, together with mild hypoalbuminemia and decreased albumin/globulin ratio in 2 dogs, as well as a mild increase in the alanine aminotransferases (ALT 10–40 UI reference range) in 3 dogs." (PMID 35405807, 2022). "For patients with hypoalbuminemia, ALB supplementation should be the first priority, which matters not only for the drug treatment, but for maintaining the normal physical function." (PMID 35360734, 2022). "Blood tests were significant for anemia (hemoglobin 6.5 gram/dL), hypoalbuminemia (albumin 1.5 gr/dL) and elevated inflammatory markers (CRP 94 mg/L, normal <5 mg/L)." (PMID 36466854, 2022). "A higher percentage of patients with hypoalbuminemia—defined as serum albumin below 3.8 g/dL—was detected in the DM group (26.7 vs. 23.7%, p < 0.05)." (PMID 35057428, 2022).
Hypoalbuminemia (continued). "Earlier studies on the efficacy of albumin solutions in resuscitation predominantly focused on critically ill and patients with sepsis and hypoalbuminaemia." (PMID 35931952, 2022). "Meanwhile, serum albumin is exclusively produced by the liver and can reflect liver function, an important indicator during assessment of liver synthetic function and hypoalbuminemia that accounts for increased mortality in cirrhosis patients." (PMID 36147636, 2022). "These inflammatory cytokines suppress albumin production and increase catabolism, resulting in hypoalbuminemia." (PMID 36432541, 2022). "Some dogs in the current study had albumin concentrations below the reference range but the hypoalbuminemia was judged to be mild in the study population of stable diabetic dogs and unlikely to impact the results." (PMID 35213623, 2022). "Albumin is widely recognized as an indicator of nutritional levels, and the mechanism of hypoalbuminemia is related to the increase in two inflammatory cytokines, tumor necrosis factor-α and interleukin-6, which inhibit the synthesis of albumin." (PMID 36386541, 2022). "There were 1,078 (15.2%) patients in the pre-operative hypoalbuminemia group and 5,994 (84.8%) patients in the normal pre-operative albumin level group." (PMID 36105581, 2022). "At admission, mean SCr was 3.3±3.52 mg/dL, mean hemoglobin was 11.7±2.3 g/dL with almost 60% of patients being anemic, mean N/L ratio was 7.2±6.1, mean serum albumin was 3.3±0.5g/dL with more than half of the patients with hypoalbuminemia." (PMID 34762092, 2022). "In a retrospective case series of children who were hospitalised with the diagnosis of MIS-C in Atlanta, all 11 patients developed hypoalbuminemia and 83% of them received intravenous albumin infusion." (PMID 36254726, 2022). "Albumin infusion for hypoalbuminemia is correlated with higher illness severity and can act as a frailty biomarker among patients with heart failure or ACS." (PMID 35321103, 2022). "ERAS group had a lower incidence of severe postoperative hypoalbuminemia (serum albumin less than 30 g/L) (15.8% vs. 9.0% p < 0.01)." (PMID 35331289, 2022). "Hepatic changes correlated with decreased gluconeogenesis, while liver albumin production seems to be unaffected and hypoalbuminemia is rather a result of increased leakage into the interstitium." (PMID 36232721, 2022). "On the other hand, it can shorten albumin’s half-life and decrease its amount, resulting in hypoalbuminemia." (PMID 35709212, 2022). "The mean preoperative serum albumin level (A1) in this group was 3.28 g/dl (range: 2.8 g/dl to 3.9 g/dl) with 57.89% (22/38) of the children having hypoalbuminemia on admission." (PMID 35706741, 2022). "Proteinuria in these cases would make only a small contribution to the decrease in albumin levels, since it is reported that hypoalbuminemia is more related to marked proteinuria (UPC > 3.5)." (PMID 35350433, 2022). "In cases of patients with localized malignant diseases both moderate hypoalbuminemia (<34 g/L) and a normal albumin level can occur." (PMID 35173556, 2022). "Note the dramatic difference in survival among patients with hypoalbuminemia vs. those with normal serum albumin in all three patient populations." (PMID 35268297, 2022). "By contrast, hypoalbuminemia was corrected in FcRn KO mice, indicating its central role in transcytotic albumin retrieval in the nephrotic state." (PMID 36139492, 2022). "The adverse effect of low albumin levels in OS and PFS was consistent across tumor type, albumin cut-off for hypoalbuminemia, study country, and study sample size." (PMID 36533070, 2022). "Albumin infusion and normal protein diet administration methods are commonly practiced in the wound treatments of hypoalbuminemia patients." (PMID 35160450, 2022).
Hypoalbuminemia (continued). "In our study, we found that patients with a lower BMI, a higher ALB concentration, and a higher HGB concentration had a better response to NAC, which proves that obesity, hypoalbuminemia, and anemia are all risk factors for the pCR." (PMID 35756481, 2022). "To clarify the prognostic impact of pre-treatment hypoalbuminemia, we performed a Kaplan-Meier survival analysis and log-rank test: the 1-year OS rate in the albumin-low group was 26.1%, and that in the albumin-high group was 77.4% (p = 0.004)." (PMID 36054114, 2022). "Hypoalbuminemia (serum albumin < 2.8 g/dL) on the first day after major head and neck surgery is associated with an increased risk of postoperative complications." (PMID 33875388, 2022). "Hypoproteinemia can also be caused by liver impairment, which reduces the synthesis of plasma proteins like albumin (hypoalbuminemia)." (PMID 35097134, 2022). "Treatment with 20% albumin also improved organ function in critically ill patients with hypoalbuminaemia." (PMID 35931952, 2022). "Serum albumin concentration at admission was available in only 72 patients, 34 of whom had hypoalbuminemia (reference range: 2.7–3.6 g/dL)." (PMID 36313832, 2022). "Our results indicated a significant decrease in albumin (hypoalbuminemia) and globulin content in C. gariepinus exposed to dexamethasone." (PMID 36187758, 2022). "All had elevated CRP levels, median 226 mg/L (IQR 122.5–361), and hypoalbuminemia, with a median albumin value of 2.2 g/L (IQR 1.84–2.46)." (PMID 35967584, 2022). "It’s worth noting that the incidence of hypoalbuminemia (albumin < 3.5 g/dL) is as high as 80.23% (568/708) in the overall patient population in our study." (PMID 36112320, 2022). "In our study, ALB levels decreased significantly during the recovery process of infected hamsters, similar to a previous study showing hypoalbuminemia in Nipah virus-infected hamsters." (PMID 35196799, 2022). "In patients with hypoalbuminemia, adequate replacement of albumin and fresh frozen plasma is necessary and perioperative intravenous fluids should be restricted properly." (PMID 35025947, 2022). "Eight studies reported the incidence of any complications in patients with hypoalbuminemia and normal albumin levels." (PMID 36684211, 2022). "In fact, inflammatory processes that reduce albumin levels and hypoalbuminemia (serum albumin levels <3.5 g/dL) have been used as a predictor of poor outcomes and high mortality in acute critically ill patients." (PMID 35160039, 2022). "As a rule, the establishment of hypoalbuminemia requires intravenous administration of human serum albumin in critically ill COVID-19 patients." (PMID 36552520, 2022). "Of these, 333 (89.5%) patients developed hypoalbuminemia, whereas 39 (10.5%) patients remained normal albumin levels after craniotomy." (PMID 34996896, 2022). "Nevertheless, the lowest albumin level in our study population was 3.9 g/dL, which is above 3.5 g/dL, which is a cut-off value for hypoalbuminemia." (PMID 35682159, 2022). "Hypoalbuminemia is a biomarker for inflammatory load in the body because inflammation can lower the rate of albumin production and increase albumin catabolism." (PMID 36712669, 2022). "Laboratory tests showed anemia (Hb 7.2 g/dL), mildly elevated eosinophil percentage (up to 10.4%, absolute count 1,050/μL), thrombocytosis (platelet 825,000/μL), hypoalbuminemia (albumin 1.94 g/dL), normal INR, and normal CRP levels." (PMID 35450101, 2022). "Hypoalbuminemia (i.e., albumin <3.4 g/dL) was observed in 56 patients who died (56%) and 167 who were discharged (28%)." (PMID 35664387, 2022). "Overall, 65% of the study population had preoperative hypoalbuminemia (serum albumin level <3.5 g/dL)." (PMID 36589182, 2022). "Hypoalbuminemia among adults is defined as serum albumin level below 3.5 g/dL but levels under 2.5 g/dL are often considered clinically significant." (PMID 35189828, 2022).